RN7SL267P (RNA, 7SL, cytoplasmic 267, pseudogene)
Gene: Miscellaneous RNA gene on chromosome 2 (182,314,284 to 182,314,544, forward strand). Ensembl gene ENSG00000242121.
Homologues: Orthologues: chimpanzee Metazoa_SRP (99% identical), macaque Metazoa_SRP (89% identical), dog Metazoa_SRP (56% identical). Paralogues in human: RN7SL3 (83% identical), RN7SL1 (82% identical), RN7SL2 (81% identical), RN7SL45P (81% identical), RN7SL743P (81% identical), RN7SL414P (81% identical), RN7SL607P (81% identical), RN7SL679P (80% identical), RN7SL218P (80% identical), RN7SL230P (80% identical), RN7SL566P (80% identical), RN7SL769P (80% identical), and 702 more.